CHI3L1 (chitinase 3 like 1)
Diseases named in the same sentence as CHI3L1 in open-access papers (continued):
Sharing a sentence is not in itself a finding about the gene and the disease.
lung carcinoma (continued). "Intervention of the CSF1/CSF1R and IL-6/IL-6R ligand-receptor pairs significantly reduced the ability of CHI3L1 lung cancer cells to recruit macrophages." (PMID 41362730, 2026). "Their study developed a humanized anti-CHI3L1 antibody, which exhibited strong anti-tumor and anti-metastatic effects in a lung cancer mouse model, effectively suppressing tumor growth and dissemination." (PMID 40260255, 2025). "Significantly elevated serum CHI3L1 has been observed across major lung cancer subtypes, including adenocarcinoma, squamous cell carcinoma, and small cell lung carcinoma." (PMID 40643503, 2025). "In an inflammation-induced lung cancer model, CHI3L1 expression was significantly upregulated and positively correlated with tumorigenesis." (PMID 40643503, 2025). "High CHI3L1 expression has also been reported in lung cancer tissues and patient serum, where levels increase with disease stage and correlate with poor prognosis." (PMID 40643503, 2025). "CHI3L1 is known to play a significant role in the development and progression of lung cancer, promoting tumor cell invasion and metastasis." (PMID 38177294, 2024). "Based on the preliminary findings from the Open Targets Platform and STRING analyses, CHI3L1 exhibits interesting potential as a candidate biomarker for further investigation in lung cancer prediction." (PMID 38177294, 2024). "Our previous study found that K284-6111 and Ebractenoid F, which are small-molecule inhibitors of CHI3L1 activity, yielded promising results in preclinical studies regarding the inhibition of the growth and metastasis of lung cancer cells." (PMID 38177294, 2024). "The compound K284 with a CHI3L1 chitin-binding domain can effectively inhibit the binding of CHI3L1 to its receptor, IL-13Rα2, to suppress lung cancer metastasis." (PMID 39068486, 2024). "CHI3L1 is a potential biomarker for the prediction of local and systemic inflammation-induced lung cancer in animal models." (PMID 39068486, 2024). "Overall, the interactions of CHI3L1 contribute to inflammation, tumor growth, and survival in lung cancer." (PMID 38177294, 2024). "In this study, we found that CHI3L1 induces autophagy in lung cancer cell by increasing the formation of autophagosomes and autolysosomes." (PMID 37340009, 2023). "Many studies have shown that decreased expression of CHI3L1 is effective in treating cancer cells by inhibiting the metastasis of lung cancer and inducing apoptosis." (PMID 37340009, 2023). "Under ER stress-induced by thapsigargin treatment, the depletion of CHI3L1 greatly increased PERK protein levels in lung cancer cells." (PMID 37215572, 2023). "Based on these results, the effect and mechanism of CHI3L1 on autophagy in lung cancer were investigated." (PMID 37340009, 2023). "In CHI3L1-overexpressing lung cancer cells, the expression of LC3, an autophagosome marker, and the accumulation of LC3 puncta increased." (PMID 37340009, 2023). "To verify the effect of CHI3L1 depletion on ER stress-mediated cancer cell death in lung cancer cells, we performed MTT assay." (PMID 37215572, 2023). "It was also found that CHI3L1 and Grp78 interact higher in lung cancer cells than normal lung cells." (PMID 37215572, 2023). "LC3 puncta was decreased in only siRNA CHI3L1-transfected lung cancer cells and also decreased with combination treatment with siRNA CHI3L1 and HCQ compared with siRNA control and HCQ." (PMID 37340009, 2023). "Based on these results, this study investigated the effect of high expression of CHI3L1 on autophagy in lung cancer cells and its basic molecular mechanisms." (PMID 37340009, 2023). "Next, we analyzed the change in the expression of CHI3L1 and autophagy-related proteins using human lung cancer tissues." (PMID 37340009, 2023).
lung carcinoma (continued). "In this study, we found that LC3 expression and LC3 puncta formation increased in CHI3L1-overexpressing lung cancer cells." (PMID 37340009, 2023). "Early studies have shown that CHI3L1 is highly expressed in a variety of tumor tissues, such as gastric cancer, lung cancer, and ovarian cancer." (PMID 37480002, 2023). "Here, we showed that the depletion of CHI3L1 induces ER stress-mediated lung cancer cell death through SOD1 upregulation." (PMID 37215572, 2023). "As it is important to understand the precise biological function of CHI3L1 in lung cancer, we investigated the potential novel pathophysiological function of CHI3L1 in lung tumorigenesis." (PMID 37215572, 2023). "We found that CHI3L1 overexpression significantly increased LC3 puncta accumulation in lung cancer cells." (PMID 37340009, 2023). "We also investigated cell cycle stage, cancer cell migration, and cell proliferation during K284 treatment in either CHI3L1 FL‐ or Δ278‐294 CHI3L1‐transfected A549 and H460 lung cancer cells." (PMID 34758182, 2022). "The interaction of ebractenoid F-Sepharose 4B and 6B beads with lung cancer cells transfected with myc-tag CHI3L1 (cell lysates) was assessed using a pull-down assay." (PMID 36615523, 2022). "To verify the expression of Chi3L1 in lung cancer, we determined the protein level of Chi3L1 in human lung cancer patients and found that it was overexpressed in the serum and tissue of lung cancer patients compared with its controls." (PMID 34861103, 2022). "Our previous GWAS/OMIM/DEG analysis results demonstrated a substantial correlation between CHI3L1 and lung cancer development." (PMID 36615523, 2022). "A high level of Chi3L1 is correlated with poor prognosis in various human carcinomas such as leukemia, lymphoma, breast cancer, and lung cancer." (PMID 34861103, 2022). "Our previous study found Chi3L1 to be highly relevant for lung cancer compared with other targets including EGF." (PMID 34861103, 2022). "The sensitivity and specificity of serum Chi3L1 in lung cancer diagnosis are 85% and 85%, respectively." (PMID 34861103, 2022). "Several studies demonstrated that high levels of CHI3L1 were expressed in lung cancer patient tissue and serum, and lung metastasis was decreased in Chi3L1 depleted mice." (PMID 34758182, 2022). "The protein expression of CHI3L1, IL‐13Rα1, and IL‐13Rα2 was significantly higher in tumor tissues than in normal tissues of lung cancer patients." (PMID 34758182, 2022). "We evaluated the tumor growth inhibition of the anti‐Chi3L1 antibody using a cell line‐induced lung cancer model via subcutaneous injection of LLC cells." (PMID 34861103, 2022). "VEGF, PD‐L1, and CEACAM are important targets for lung cancer, and we confirmed the importance of Chi3L1 in lung cancer diagnosis." (PMID 34861103, 2022). "Clinically, high plasma level or intratumoral expression of CHI3L1 correlated with poor survival in 161 lung cancer, 155 pancreatic cancer and 180 colon cancer patients." (PMID 34987649, 2022). "The anti‐Chi3L1 antibody attenuated tumor growth and metastasis both in vitro and in vivo in a lung cancer mouse model." (PMID 34861103, 2022). "In this study, we demonstrate that Chi3L1 serum and tissue levels were significantly increased in lung cancer patients compared with controls." (PMID 34861103, 2022). "We compared other lung cancer biomarkers, vascular endothelial growth factor (VEGF), programmed cell death 1 ligand 1 (PD‐L1), and carcinoembryonic antigen (CEACAM), with Chi3L1 in the serum of lung cancer patients." (PMID 34861103, 2022). "In this study, we confirmed that the anti‐Chi3L1 antibody has an important effect on tumorigenesis, cancer metastasis, and macrophage polarization in a lung cancer model." (PMID 34861103, 2022). "In the tissue samples from lung cancer patients, the protein expression of CHI3L1, IL‐13Rα1, and IL‐13Rα2 and the phosphorylated levels of c‐Jun, c‐Fos, AKT, and ERK were elevated compared with those in normal lung tissues." (PMID 34758182, 2022).
lung carcinoma (continued). "Despite extensive evidence regarding the role of CHI3L1 and its downstream signals in lung tumor growth, knowledge regarding compounds disrupting CHI3L1-specific downstream signaling, and consequently, preventing lung cancer growth, is limited." (PMID 36615523, 2022). "We demonstrated that the pharmacologic inhibition of Chi3L1 using humanized antibody anti‐Chi3L1 antibody attenuates lung tumor growth and metastatic node formation in lung cancer." (PMID 34861103, 2022). "We demonstrated that the selective CHI3L1 inhibitor K284 strongly inhibits lung cancer cell growth and tumor metastasis." (PMID 34758182, 2022). "High serum levels of CHI3L1 correlate with poor prognosis and survival in various human carcinomas, including lung cancer." (PMID 34758182, 2022). "Herein, we screened several natural compounds using a luciferase activity assay, and selected ebractenoid F as a candidate compound, because it showed strong inhibitory activity against CHI3L1 and has notable cytotoxic effects against lung cancer cells." (PMID 36615523, 2022). "In this study, we analyzed how blocking Chi3L1 protein with anti‐Chi3L1 humanized antibody affects the progression of lung cancer in a xenograft mouse model." (PMID 34861103, 2022). "We also tested the inhibitory effects of these selected 11 compounds, which can bind to CHI3L1, on lung cancer cell growth." (PMID 34758182, 2022). "In our previous study, we found that CHI3L1-inhibiting compound K284 inhibited lung tumor metastasis and lung cancer cell growth via the inhibition of AKT signaling." (PMID 36615523, 2022). "High levels of Chi3L1 expression were correlated with poor overall survival in lung cancer patients (lung adenocarcinoma)." (PMID 34861103, 2022). "The serum Chi3L1 analysis results of each stage of lung cancer show that the AUC value was more than 0.9." (PMID 34861103, 2022). "A549 lung cancer cells were treated with K284 and then purified the cytosolic protein containing CHI3L1 and IL‐13Rαs to perform immunoprecipitation." (PMID 34758182, 2022). "We also found that the level of Chi3L1 significantly was elevated in serum of human lung cancer patient compared to normal serum." (PMID 32127023, 2020). "To clear the expression of Chi3L1 on the lung tumor development in human, we performed Western blot assay using tumor tissues of human lung cancer patient." (PMID 32127023, 2020). "Immunofluorescence data exhibited that Myc-tagged full-length Chi3L1 (myc-Chi3L1) was present in the cytoplasm and nucleus of the lung cancer cells." (PMID 32127023, 2020). "This study demonstrated that the expression of Chi3L1 was significantly increased in tumor tissues of human lung cancer patient compared to human normal lung tissues." (PMID 32127023, 2020). "In the present study, we also found that Chi3L1 is placed within the cytoplasm and nucleus in the lung cancer cells." (PMID 32127023, 2020).
lung carcinoma (continued). "Considering that high serum Chi3L1 is a poor prognostic marker in lung cancer patients, it should be investigated for intracellular Chi3L1 expression and direct roles and mechanisms on lung tumorigenesis by intracellular Chi3L1." (PMID 32127023, 2020). "Most proinflammatory factors activate STAT3, and chitinase 3-like 1 that is a downstream gene of the STAT3 signaling pathway is a potential biomarker to predict inflammatory lung cancer in a STAT3-induced mouse lung cancer model." (PMID 31832112, 2019). "The CHI3L1 protein was significantly elevated in human serum samples from all types of lung cancers and recombinant CHI3L1 stimulated proliferation and growth of Lewis lung carcinoma cells." (PMID 26425658, 2015). "When tested in other inflammation-induced lung cancer mouse models, the CHI3L1 protein concentration was also highly increased in BALF and blood of these models with tumors." (PMID 23613996, 2013). "In summary, this report shows that CHI3L1 is a potential biomarker for inflammation-induced lung cancer prediction in animal models, especially in Stat3-induced cancer." (PMID 23613996, 2013). "Although CHI3L1 is a useful biomarker, it is necessary to use multiple biomarkers as a panel for more accurate prediction and verification of lung cancer, as increase of CHI3L1 expression has been shown in other inflammation-related mouse models." (PMID 23613996, 2013). "This provides a significant mechanistic insight into the inflammation-induced lung cancer formation; 3) The animal models used in our work are unique, which give us a unique opportunity to study the basic and clinical directions of CHI3L1." (PMID 23613996, 2013). "Analysis of normal objects and lung cancer patients revealed a significant elevation of CHI3L1 protein concentration in human serum samples from all categories of lung cancers." (PMID 23613996, 2013). "It is important to keep in mind that the CHI3L1 upstream Stat3 oncogene is up-regulated in both human lung cancer and COPD." (PMID 23613996, 2013). "Similarly, in lung cancer, particularly non-small cell lung cancer, CHI3L1 expression is elevated in both serum and tumor tissue." (PMID 40643503, 2025). "If we sum the text-mining scores listed for NSCLC and small cell lung cancer, lung cancer may be the top disease related to CHI3L1." (PMID 38177294, 2024). "CHI3L1 regulates the IL-13 signaling pathway through IL-13Rα2, leading to increased secretion of cytokines, such as IL-1β and IL-6, which can influence inflammation in lung cancer." (PMID 38177294, 2024). "Overall, given the strong evidence linking CHI3L1 to lung cancer formation and progression, targeting this protein may be a promising strategy for the development of new therapies and diagnostic tools for this deadly disease." (PMID 38177294, 2024). "In contrast, CHI3L1 depletion in lung cancer cells decreased the formation of autophagosomes." (PMID 37340009, 2023). "This study attempted to investigate the effect of CHI3L1 on autophagy in lung cancer." (PMID 37340009, 2023). "To determine whether JNK depeldent CHI3L1-induced autophagy resulted in the inhibition of the lung cancer cell invasion, we performed trans-well assay." (PMID 37340009, 2023). "However, when JNK signaling is inhibited by SP600125 treatment, CHI3L1 overexpression induced cell viability was prevented in lung cancer cells." (PMID 37340009, 2023). "In addition, the depletion of CHI3L1 significantly increased the expression of ER chaperone proteins in ER stress conditions in lung cancer cells." (PMID 37215572, 2023). "However, under SP600125 treatment, CHI3L1 overexpression-induced cell viability was prevented in lung cancer cells." (PMID 37340009, 2023).
lung carcinoma (continued). "Furthermore, our results showed that CHI3L1 overexpression induces cell proliferation and invasion in lung cancer cells." (PMID 37340009, 2023). "Furthermore, the expression of autophagy-related proteins and CHI3L1 increased in lung cancer tissues compared with normal lung tissues." (PMID 37340009, 2023). "The pro-survival effects of CHI3L1-induced autophagy may be counteracted by the pro-apoptotic effects of JNK inhibition in lung cancer cells." (PMID 37340009, 2023). "CHI3L1 overexpression increased the invasion in lung cancer cells." (PMID 37340009, 2023). "We have reported the importance of CHI3L1 in tumor development, especially lung cancer 22-27." (PMID 37215572, 2023). "In addition, Myc-CHI3L1-transfected lung cancer cells showed an extensive distribution of fluorescent LC3 puncta patterns, which were further increased with HCQ treatment." (PMID 37340009, 2023). "CHI3L1 is found to be involved in the malignancy of breast cancer, melanoma and lung cancer, etc.." (PMID 37480002, 2023). "The expression of the autophagosome marker protein LC3 was confirmed to determine whether CHI3L1 induces autophagy in lung cancer cell lines including A549 and H460 cells." (PMID 37340009, 2023). "We confirmed that JNK phosphorylation was elevated in CHI3L1-overepxressing lung cancer cells." (PMID 37340009, 2023). "In addition, several studies have shown that CHI3L1 knockdown inhibits lung cancer cell proliferation and promotes cancer cell death." (PMID 37340009, 2023). "Here, we investigated whether the protein expression of CHI3L1 correlates with IL‐13Rαs and its downstream signaling in tumor samples from lung cancer patients." (PMID 34758182, 2022). "We further analyzed genetic alterations of Chi3L1 in human lung cancer using cBioPortal." (PMID 34861103, 2022). "The treatment with ebractenoid F reduced the half-life of CHI3L1 in lung cancer cells, suggesting that reduced stability by ebractenoid F could be involved in CHI3L1 expression." (PMID 36615523, 2022). "High Chi3L1 expression was correlated with poor overall survival in patients with lung cancer (LC)." (PMID 34861103, 2022). "Chi3L1 was stage dependently increased in serum and tissue of human lung cancer patients." (PMID 34861103, 2022). "A recent study reported that CHI3L1 regulated PD-L1 and anti-CHI3L1-PD-1 antibodies to elicit synergistic antitumour responses, reflecting that CHI3L1 might constitute a target to augment the efficacy of anti-PD-1 in lung cancer." (PMID 36581917, 2022). "To determine whether ebractenoid F binds to CHI3L1 and inhibits lung cancer cell growth by blocking the CHI3L1 signal, we first investigated the expression of CHI3L1 on ebractenoid F treatment." (PMID 36615523, 2022). "In addition, several other studies have reported that CHI3L1 is an important factor in lung cancer metastasis." (PMID 36615523, 2022). "Anti‐Chi3L1 antibody treatment attenuated tumor growth, metastasis in a lung cancer mouse model." (PMID 34861103, 2022). "We examined whether the infiltrating M2 tumor associated macrophages (M2 TAM, CD163+) were enriched in the area of Rab37+CHI3L1+ cells in tumor specimens from lung cancer patients." (PMID 34987649, 2022). "In this present study, we investigated whether a CHI3L1-inhibiting natural compound, ebractenoid F, inhibits lung cancer cell growth and migration and induces apoptosis." (PMID 36615523, 2022). "Chi3L1 plays a critical role in lung cancer progression, and the anti‐Chi3L1 antibody could be a new anticancer therapy." (PMID 34861103, 2022). "CHI3L1 has been reported to activate its downstream signaling pathways, such as protein kinase B, also known as AKT, and Wnt/β-catenin, as well as MMP signaling pathways, which have been reported to be significantly associated with lung cancer cell growth." (PMID 36615523, 2022).